CAT (catalase)
Diseases named in the same sentence as CAT in open-access papers (continued):
Sharing a sentence is not in itself a finding about the gene and the disease.
parasitic infection (10 papers, 2019 to 2025). "CAT enzymatic activity has been studied in various compartments of the eye in humans and model organisms, and reduced CAT activity was linked to decreased parasitosis." (PMID 32859251, 2020). "In response to parasite infection, the expression of CAT and GST-mu was observed to be down-regulated." (PMID 38275638, 2023). "The percentage reduction of parasitemia was related to each test, and the liver homogenate was used to assay malondialdehyde, superoxide dismutase, nitrogen monoxide, catalase, and glutathione for the evaluation of oxidative stress." (PMID 37637978, 2023). "In the CAT group, 11 of 16 (63.8%) immunized subjects developed parasitemia (mean 13.0 days), indicating significant protection by log rank test compared to infectivity controls (p = 0.0406) and the CA group (p = 0.0229)." (PMID 34495988, 2021). "The ANOVA results indicated that the activity of CAT and POX was significantly affected only by the main effect of parasitic infection." (PMID 40166631, 2025). "Estimation of serum enzymatic antioxidant activities in parasitic infection such as GSH-PX, SOD, and CAT were means of assessing the oxidative stress." (PMID 31528024, 2019). "The parasitic infection led to increased activities in antioxidant enzymes such as catalase (CAT) and peroxidase (POX) in stems, but not in leaves." (PMID 41465831, 2025). "The study demonstrated that T. equi infection leads to immune system suppression by significantly increasing the levels of oxidative stress markers (CAT, GPx, MDA, and SOD) (P ≤ 0.0001), with this elevation being directly proportional to parasitemia levels in infected blood cells." (PMID 38967736, 2024). "Moreover, the production of this massive amount of ROS and NOS in parasitic diseases can exhaust both low molecular antioxidants such as vitamin A, E and C and metal-dependent antioxidants such as GPX, SOD and CAT." (PMID 37237892, 2023). "In the CAT group, 5 of 16 (31%) immunized subjects did not develop parasitemia, and the remaining 11 subjects became parasitemic between days 11 to 17 (mean 12.9 days), an interval similar to that seen in the parasitemic subjects in the CA and infectivity control groups." (PMID 34495988, 2021).
pneumonia (10 papers, 2017 to 2025). An acute, acute and chronic, or chronic inflammation focally or diffusely affecting the lung parenchyma, caused by an infection in one or both of the lungs (by bacteria, viruses, fungi, or mycoplasma.). "In contrast, methicillin-resistant Staphylococcus aureus (MRSA), a coagulase and catalase-positive Gram-positive organism, is frequently associated with a spectrum of infections, ranging from skin infections to severe conditions such as pneumonia and endocarditis." (PMID 40861738, 2025). "In addition, there appears to be a preponderance of pneumonia caused by Haemophilus influenza and Klebsiella pneumoniae bacteria in alcoholic patients, both of which are also catalase positive." (PMID 26860769, 2017). "In sheep with pneumonia, CAT (0.35 ± 0.11) was the most downregulated, whereas IL-1α (2.66 ± 0.08) was the most upregulated." (PMID 40221769, 2025). "In mice, CAT was able to suppress the inflammatory response by promoting a protective role against pneumonia." (PMID 33381273, 2020). "Biologically, catalase is found to have potential therapeutic effectiveness against influenza-induced pneumonia." (PMID 32805728, 2020). "The survival time and rates of mice with H1N1-induced pneumonia were increased by treatment with recombinant human CAT." (PMID 33381273, 2020). "In our opinion, this is the first study to identify SNPs in antioxidant (SOD1, CAT, GPX1, NOS, HMOX1, and NQO1) and immunological (IL-1α, IL1B, IL6, TNF-α, IL10, LFA-1, CR2, IL17, IL13, DEFB123, SCART1, and ICAM1) genes as potential suspects for pneumonia resistance/susceptibility in Barki ewes." (PMID 40221769, 2025). "Conversely, the expression levels of IL10, SOD1, CAT, GPX1, and NQO1 were significantly lower in the pneumonia group than in the healthy control group." (PMID 40221769, 2025). "Given the strong protective effect of NS1619 on ROS production, we further investigated its impact on oxidative stress mechanisms relevant to pneumonia, including SOD, catalase, H2O2 levels, and GSH/GSH ratios." (PMID 40830381, 2025). "To unequivocally determine the impact of hsdSA on the phase variation known as switch between transparent and opaque phenotypes of pneumonia, we observed the colony morphology on soybean casein digest agar (TSA) plates supplemented with catalase under a dissection microscope." (PMID 38018988, 2024). "In the presence of catalase, the rate of cell death was significantly reduced in both healthy controls (~4%) and in patients with A-T (~36%) at 8 h, indicating that H2O2 produced by S. pneumonia plays a major role in the killing observed." (PMID 30796268, 2019).
preeclampsia (10 papers, 2009 to 2025). Preeclampsia is a hypertensive disorder of pregnancy that is characterized by new-onset hypertension with proteinuria presenting after 20 weeks of gestation, and depending on mild or severe forms may initially present with severe headache, visual disturbances, and hyperreflexia. "It has been suggested that CAT is compensatively increased in preeclampsia, or that decreased CAT increases the risk of preeclampsia." (PMID 40123939, 2025). "The activity of SOD, CAT, and GPX has been observed to decrease in the placenta of women with preeclampsia, and lower CAT activity has been linked to premature births." (PMID 37238667, 2023). "Though the higher level of GPx has been found in preeclampsia, the changing activities of CAT remain controversial." (PMID 40123939, 2025). "A recent meta-analysis evidences similar findings in women with preeclampsia, showing an increase in catalase serum activity but unchanged or decreased SOD." (PMID 33379399, 2020). "Critical tests of this hypothesis would be to recreate preeclampsia symptoms by inducing oxidative stress in WT animals or to ameliorate by treating mutant mice with Mn-SOD-catalase mimetics or activators of PHD." (PMID 19146669, 2009). "Moreover, reduced activity of GPx during pregnancy could be associated with hypertension of preeclampsia and spontaneous abortion, while decreased activity of CAT was proposed as a promising predictor for preeclampsia." (PMID 33809854, 2021). "Increased catalase activity in the pair-matched cord blood could be interpreted as an effort to counteract the overproduction of reactive oxygen species and provide a relief to enhanced oxidative damage in preeclampsia." (PMID 22493649, 2009). "Previous study demonstrated that the levels of SOD, CAT, and GSH were significantly lower in women with PE than in healthy women, suggesting that the antioxidant protective capacity was decreased in women with preeclampsia." (PMID 33542786, 2021).
cholestasis (9 papers, 2010 to 2024). Impairment of the bile flow caused by obstruction within the liver, or outside the liver in the bile duct system. "IGSM significantly reduced MDA levels and enhanced the activities of CAT, GSH-Px, and SOD in rats with ANIT-induced cholestasis in this study." (PMID 39408937, 2024). "In conclusion, the current study demonstrates that GPx, CAT, and GSH levels are low in patients with BA cholestasis." (PMID 26064908, 2015). "In this study, IGSM alleviated ANIT-induced cholestasis and liver injury in rats by decreasing the serum levels of AST, ALT, TBA, and AKP; decreasing the MDA level and increasing the SOD, CAT, and GSH-Px activities in the liver tissues; and increasing the mRNA levels of Fxr, Bsep, Mrp2, and Ntcp." (PMID 39408937, 2024). "Our study showed a significant increase in hepatic tissue SOD, GPx and CAT activities in patients with cholestasis compared with control group; SOD, GPx and CAT were significantly increased in the EHBA group, whereas GPx and CAT were significantly increased in both NH and PIBD groups." (PMID 20339177, 2010).
hyperuricemia (9 papers, 2016 to 2024). An abnormally high level of uric acid. "It has been shown that in the OA-induced hyperuricemia rats model, there was a decrease in the activities of key anti-oxidant enzymes such as CAT, SOD, GR, GSH-Px, and aconitase." (PMID 38911247, 2024). "Hyperuricemia decreased catalase, and GSH and GPX levels but these returned to nearly control levels after PAR and CEL administration." (PMID 32528050, 2020). "Therefore, in this study, we investigated one-pot enzyme-nanozyme cascade reactions using urate oxidase (UOX) and catalase-mimic gold nanoparticle nanozyme (AuNP) with the ultimate goal of treatment of hyperuricemia." (PMID 28287162, 2017). "We found that hyperuricemia-induced mice exhibited an increase in the MDA levels and a decrease in the activities of antioxidant enzymes, including SOD, CAT, and GPx, compared with those in the normal control group." (PMID 34451714, 2021). "These animals were treated with oxonic acid and UA to induce hyperuricemia and were administered PEG-SOD, catalase, and epalrestat." (PMID 32565731, 2020).
Arrhythmia (8 papers, 2013 to 2025). Any cardiac rhythm other than the normal sinus rhythm. "CAT activity in patients with arrhythmia was significantly lower by about 11% compared to patients from the ERI group (37.7 ± 6.00 vs. 42.5 ± 3.80 kU/g Hb)." (PMID 38028798, 2023). "In the control series, stretch significantly modified the complexity of the CaT propagation patterns of HL-1 cells during the arrhythmia." (PMID 32848863, 2020). "Similar to the effects of catalase, PC-specific overexpression of both the cytosolic and mitochondrial isoforms of SOD (SOD1 and SOD2) increased the incidence of cardiac arrhythmia and caused constriction of the heart tube." (PMID 24656823, 2014). "The recent developments made in the field of indicators engineering and fluorescence microscopy not only allowed for the study of more complex arrhythmia and cardiotoxicity but also greatly improved the signal-to-noise ratios and facilitated the simultaneous recording of both AP and CaT in vitro." (PMID 37681899, 2023). "Interestingly, we found that overexpression of catalase or D-p38bDN in PCs during the embryonic and larval stages only resulted in significant cardiac arrhythmias compared to the controls." (PMID 24656823, 2014). "Therefore, we conclude that oxidative stress could significantly disrupt the ion hemostasis under the CaMKII overexpression scenario, during which the stability of AP and CaT would decrease, which might become the origin of AF and cardiac arrhythmias." (PMID 33391023, 2020). "This supports our results that SOD2 KD shows increased CaT loss and contractile dysfunction compared to SOD1 in iAMS and only SOD2 KD, but not SOD1 KD, induced arrhythmia in Drosophila." (PMID 41462644, 2025). "Et postconditioning (Etpost) significantly reduced the infarct size, arrhythmia score, ventricular fibrillation incidence, and enhanced the hemodynamic parameters by decreasing the MDA level and increasing expression of Nrf2, SOD and CAT activities." (PMID 34823510, 2021).
brain tumors (8 papers, 2018 to 2025). "Specifically, catalase levels have been found to be decreased in the nucleus and mitochondria of brain tumor cells." (PMID 41009025, 2025). "Initial studies demonstrated that compared to normal brain tissue, brain tumor tissue exhibits considerably less H2O2 detoxification by CAT." (PMID 41009025, 2025). "Compared to normal brain tissue, brain tumor tissue exhibits considerably less H2O2 detoxification by CAT." (PMID 36307808, 2022). "Single nucleotide polymorphisms of OS-responsive genes, such as CAT, SOD1, SOD2, SOD3, GPx1, NOS3, and PON1 have been found in adult brain tumor studies." (PMID 36307808, 2022). "CAT level has been found to be decreased specifically in the nucleus and mitochondria of brain tumor cells." (PMID 36307808, 2022). "On the contrary, other reports showed that CAT levels were significantly increased in brain tumor tissue." (PMID 36307808, 2022). "Compared with the control group, patients with various forms of brain tumors showed a statistically insignificant decrease in CAT levels." (PMID 36307808, 2022). "The involvement of ROS in brain cancerogenesis is currently being actively studied: previous studies have emphasized that enzyme-like malonyl dialdehyde (MDA) level, superoxide dismutase (SOD), and catalase (CAT) activities results were altered in brain tumor tissue." (PMID 36902485, 2023). "Super-oxide dismutase and catalase (CAT) activity are particularly studied in brain tumors." (PMID 37895109, 2023). "Thus, modulation of redox status in brain tumor cells by regulating CAT expression could serve as a potential therapeutic approach in brain cancer management." (PMID 36307808, 2022). "In addition to these, endogenous enzymatic antioxidants, such as SOD, CAT, GPx, GR, GST etc. and non-enzymatic antioxidants like GSH may act as potential OS biomarkers for brain tumors." (PMID 36307808, 2022).
co-infection (8 papers, 2019 to 2025). "In this study, POD and APX enzyme activities increased under co-infection of Rs and Pp, but the activity of CAT reduced under co-infection." (PMID 40415941, 2025). "Consistent with previous findings, we found that Jejunal H2O2 and MDA contents were increased, and T-AOC, SOD, CAT, and GSH-Px levels were decreased by CCP challenge, which indicated that CCP co-infection caused oxidative stress in the broiler." (PMID 38540053, 2024). "In the present study, co-infection with coccidia and C. perfringens decreased the activities of CAT, T-SOD, and GSH-Px." (PMID 36496951, 2022). "In this regard, co-infection with lenti-MnSODK68R and AdMitoCat, which expresses catalase and decreases cellular hydrogen peroxide, prevented transformation (right column)." (PMID 31160585, 2019). "KatA has been reported to produce catalase in A. actinomycetemcomitans strain VT1169 (Aa VT1169) to detoxify H2O2 and is essential for the survival of A. actinomycetemcomitans during co-infection with S. gordonii." (PMID 30894650, 2019). "Moreover, gastric lesions can induce oxidative stress, with amplification by OME therapy independently of co-infection with H. pylori, and also increase antioxidant enzymes such as SOD and CAT, and glutathione reductase (GSH)." (PMID 35436881, 2022). "Thus, based in previous investigations, the present study aimed to evaluate cytogenetic damages in patients whith gastritis undergoing OME therapy, with and without H. pylori co-infection, through micronucleus test and expression of catalase and superoxide dismutase." (PMID 35436881, 2022).
fibrosis (8 papers, 2018 to 2025). the formation of excess fibrous connective tissue in an organ or tissue in a reparative or reactive process. "In the group of patients with early NAFLD (patients without fibrosis in elastography and normal ALT activity), similar CAT levels were found in the group of patients with advance NAFLD (with fibrosis and upper ALT activity)." (PMID 37759451, 2023). "Such cardiac fibrosis was reduced by catalase overexpression and accentuated by mitochondrial sirtuin SIRT3 deficiency, in transgenic mice." (PMID 29763629, 2018). "Moreover, we detected a gradual decrease in catalase protein level in mouse lungs after bleomycin-induced fibrosis, remarkably from day 14 after treatment." (PMID 39313791, 2024). "Liver SOD and CAT activities and GSH level in nontreated animals which experienced 10-week fibrosis were maintained at the control level." (PMID 32148657, 2020).
nematode infection (8 papers, 2019 to 2024). "SA treatment of resistant plants induced a significant decrease in CAT in root extracts, similar to that induced by nematode infection." (PMID 37108485, 2023). "MYB also induces the defense response by co-interaction with SOD and catalase enzymes in relation to nematode infection." (PMID 37510240, 2023). "A catalase gene (CAT)was highly over-expressed by nematode infection, however, this over-expression was annulled at the earliest stages or limited at the later stages of infection toBCA-treated roots." (PMID 31794550, 2019). "Studies have shown that resistant genotypes of plants infected with root-knot nematodes exhibit higher SOD activity compared to susceptible genotypes, indicating a protective response against nematode infection, whereas CAT activity in resistant genotypes decreases upon infection." (PMID 38666879, 2024). "Therefore, it was decided to investigate further the mechanisms of such an inhibition and to test the effect of a successful nematode infection on CAT activity." (PMID 37108485, 2023). "Therefore, it can be concluded that the observed specific CAT inhibition in roots of resistant tomato plants in the early stages of nematode infection is probably due to an increase in both H2O2 and SA." (PMID 37108485, 2023). "In the early stages of nematode infection, either the expression of antioxidant genes, such as GPX and CAT, or the activity of antioxidant enzymes, such as SOD, CAT, and APX, have herein been found to increase." (PMID 39684315, 2024). "It was reported that SOD, CAT, and APOX activities enhanced under nematode infection in various host plants (eggplant, jasmine, cowpea, orange, and papaya)." (PMID 31936090, 2020). "Similar results were also reported by Khajuria and Ohri in the case of tomato plants, where activities of SOD, POD, CAT, GPOX, etc., were enhanced during nematode infection." (PMID 32867342, 2020). "JA (100 nM) treatment resulted in enhancement in SOD activity (43.0%), POD (48.6%), CAT (52.5%), APOX (29.5%), DHAR (51.8%), GR (70.3%), and PPO (43.8%) in infected seedlings in contrast to nematode infection alone." (PMID 31936090, 2020). "In response to nematode infection, expression of SOD (3.277 folds), CAT (2.283 folds), POD (2.295 folds), and GST (1.720 folds) was significantly found enhanced in tomato seedlings as compared to non-infected ones whereas the expression of GPOX was found suppressed by 0.8878 folds." (PMID 31936090, 2020).
osteosarcoma (8 papers, 2016 to 2024). A usually aggressive malignant bone-forming mesenchymal neoplasm, predominantly affecting adolescents and young adults. "Catalase expression in osteosarcoma cells was consistently elevated in the poor response group, while Hsp70 expression was highest." (PMID 38748263, 2024). "Among the DEPs identifying oseoblastic and telangiectatic osteosarcoma subtypes are CAT, FGA, SLC4A1, and ACTA2." (PMID 37681913, 2023). "Osteosarcoma cells are characterized by high peroxidases and catalase activity, which degrades H2O2 into water and oxygen, and prevents its accumulation in lysosomes." (PMID 26927177, 2016). "Based on these data, we concluded that osteosarcoma cells are resistant to X-ray irradiation because of high peroxidases and catalase activity." (PMID 26927177, 2016). "In order to further investigate more in detail how osteosarcoma cells were challenged by OB-EVs via ROS-dependent mechanisms, we measured the specific activity of catalase, which is known to play a critical role in first line defence against oxidative stress within cells." (PMID 36544705, 2022). "As expected, catalase fully suppressed the cytotoxic potential of PAM in osteosarcoma cells." (PMID 31337843, 2019). "In MG63 osteosarcoma cells, HIF-1α was found to inhibit reactive oxygen species accumulation by directly regulating FoxO1, which interfered with CAT catalase activity, thus resulting in anti-oxidation effects." (PMID 37681913, 2023). "And many of them, such as ZNRD1, GPR68, CAT, FUT3, ANPEP, CDK1, and hsa-miR-543, might be key genes related to osteosarcoma chemoresistance." (PMID 29850522, 2018). "Among them, hsa-miR-543, as well as ZNRD1, GPR68, CAT, FUT3, ANPEP, and CDK1 genes, were proposed as crucial players in osteosarcoma chemoresistance, and hence they could represent potential therapeutic targets for osteosarcoma." (PMID 35011442, 2021).